DVL3 (dishevelled segment polarity protein 3)
Diseases named in the same sentence as DVL3 in open-access papers (continued):
Sharing a sentence is not in itself a finding about the gene and the disease.
cervical cancer (continued). "Interestingly, they were the first to demonstrate that AMPK activators, including metformin, block the growth of cervical cancer cells by interfering with the DVL3-mediated Wnt/β-catenin signaling." (PMID 37681914, 2023). "DVL3 enhances the proliferation of cervical cancer cells, and metformin reduces DVL3." (PMID 34067321, 2021). "The role of DVL3 in the inhibition of cervical cancer cells by metformin was studied." (PMID 34067321, 2021). "Our data also demonstrated that DVL3 could promote cervical cancer growth through activating Wnt/β-catenin signaling pathway." (PMID 23301094, 2013). "In fact, treatment of an mTOR inhibitor, Rapamycin, could abolish DVL3 in cervical cancer cell lines." (PMID 23301094, 2013). "We have demonstrated that ectopic expression of DVL3 could enhance cell proliferation in cervical cancer cells." (PMID 23301094, 2013). "Similarly, the DVL3 mRNA levels were significantly higher in cervical cancer cell lines as compared with the normal immortalized cervix cell lines." (PMID 23301094, 2013). "We also proposed mechanistic evidence showing that metformin, AICAR and A23187 suppress cervical cancer cell growth through reducing DVL3, a positive effector of Wnt/β-catenin signaling cascade which has been shown to be constitutively active during cervical cancer development." (PMID 23819460, 2013). "Taken together, the reduction of protein synthesis could reduce DVL3 expression in cervical cancer cell lines and that the decrement of DVL3 mediated by AMPK activators is mainly through the AMPK/mTOR signaling cascade." (PMID 23301094, 2013). "Therefore, we examined the effect of AMPK activators on the expression of DVL3 and its related Wnt/β-catenin signaling activity in cervical cancer cells." (PMID 23301094, 2013). "On the other aspect, we noted that the cervical cancer cell growth was remarkably suppressed by AMPK activators and such cell growth inhibition was in concomitant with the reduction of DVL3 protein level in dose- and time-dependent manners." (PMID 23301094, 2013). "Our findings implicate the importance of DVL3 in the cervical cancer oncogenesis and highlight the therapeutic value of targeting DVL3 by AMPK activators in cervical cancer treatment." (PMID 23301094, 2013). "Copy number alteration driven dysregulated genes, such as PI3KCA, PI3KCB, DVL3, WWTR1, and ERBB2, are believed to play an important role in regulating immune cell infiltration, which might help to predict the prognosis of cervical cancer." (PMID 34925445, 2021). "Herein, we observed that DVL3, but neither DVL1 nor DVL2, was significantly up-regulated and associated with augmented Wnt/β-catenin signaling activity and cervical cancer cell growth." (PMID 23301094, 2013). "Therefore, DVL3, a key oncoprotein in activating Wnt/β-catenin signaling, should have a higher impact on cell growth upon the treatment of AMPK activators in cervical cancer cells." (PMID 23301094, 2013). "Next, to investigate whether DVL3 promotes cell proliferation via activation of Wnt/β-catenin pathway in cervical cancer, two cervical cancer cell lines (C33A and SiHa) with stably expression of DVL3 were established using human GFP-tagged DVL3 expressing plasmid." (PMID 23301094, 2013).
colorectal cancer (7 papers, 2013 to 2025). A primary or metastatic malignant neoplasm that affects the colon or rectum. "In colorectal cancer, upregulation of Dvl2 and Dvl3, enhancing Wnt signaling, promotes metastasis progression." (PMID 40569965, 2025). "Our previous study reports that TTTY15 up-regulates disheveled segment polarity protein 3 (DVL3) expression by adsorbing miR-29a-3p, thus promoting the malignancy of colorectal cancer cells." (PMID 35287556, 2022). "For example, miR-29a-3p was reported to target on DVL3 and inhibit the proliferation, migration and invasion of colorectal cancer cells." (PMID 36471281, 2022). "However, the role and potential mechanism of DVL3 remain elusive in EMT and CSLCs of colorectal cancer (CRC)." (PMID 37147666, 2023).
hepatocellular carcinoma (5 papers, 2016 to 2025). A malignant tumor that arises from hepatocytes. "In this study, we showed that Dvl3 was significantly overexpressed in human hepatocellular carcinomas (HCCs) and promoted cancer stemness both in vitro and in vivo." (PMID 28455968, 2017). "In hepatocellular carcinoma (HCC) cells, CR-1 binds and stabilizes DVL3, helped by the concomitant binding of the Frizzled receptor FZD7 and the transmembrane lipoprotein LRP6, resulting in a more sustained signal from the Wnt/β-catenin axis." (PMID 34360603, 2021). "In hepatocellular carcinoma (HCC), PRICKLE1 negatively regulates Wnt/β-Catenin pathway by binding to DVL3 and facilitating its ubiquitination/degradation." (PMID 26939613, 2016).
ovarian carcinoma (4 papers, 2013 to 2017). A malignant neoplasm originating from the surface ovarian epithelium. "Our results, in OV2008 ovarian cancer cells, indicate that 15k, at 2 and 4 μM, significantly decreased the levels of DVL3, DVL2 and c-Myc." (PMID 28824426, 2017). "The LY6H module is altered in 24% of ovarian cancer subtype 1 cases and includes three altered genes, namely, DVL3, LY6H, and PPP1R16A." (PMID 26735889, 2016). "Thus, our analysis suggests the hypothesis that DVL3 amplifications, coupled with decrease in CXXC4 expression, could drive ovarian cancer progression through enhanced activation of the Wnt signaling pathway." (PMID 25572314, 2015).
craniorachischisis (3 papers, 2008 to 2015). Craniorachischisis is the most severe form of neural tube defect in which both the brain and spinal cord remain open to varying degrees. "For example, Dvl3+/-; LtapLp/+ can cause craniorachischisis or exencephaly." (PMID 21864354, 2011). "In the Dvl2+/−;Dvl3−/− mutants that displayed craniorachischisis, the phenotype was even more severe." (PMID 19008950, 2008). "The frequency of these defects was similar in both Dvl3+/−;LtapLp/+ (7/22, 32%, 5 with craniorachischisis and 2 with exencephaly) and Dvl3−/−;LtapLp/+ mutants (6/16, 38%, all with craniorachischisis)." (PMID 19008950, 2008). "Upon further dissection, the cochleae of the Dvl3+/−;LtapLp/+ and Dvl3−/−;LtapLp/+ mutants with craniorachischisis were also much shorter compared to controls." (PMID 19008950, 2008). "It is interesting that both exencephaly and craniorachischisis are observed in Dvl3;LtapLp mutants." (PMID 19008950, 2008). "However, craniorachischisis appears to be a more severe phenotype than exencephaly, indicating a more severe phenotype in Dvl3−/−;LtapLp/+ mutants compared to Dvl3+/−;LtapLp/+ mutants." (PMID 19008950, 2008). "Craniorachischisis was also observed in two Dvl2+/−;Dvl3−/− mutants." (PMID 19008950, 2008).
glioma (3 papers, 2013 to 2022). A benign or malignant brain and spinal cord tumor that arises from glial cells (astrocytes, oligodendrocytes, ependymal cells). "Peng at al reported that in addition to being upregulated in high-grade gliomas, CTHRC1 expression correlated with genes associated with the Wnt Signaling pathway (DVL3, DVL1, DVL2, ROR2, WNT3A, FZD6 and FZD5)." (PMID 36190948, 2022). "Genetic changes of DVL3 gene suggest its involvement in the process of glioma progression." (PMID 30468298, 2019). "Combined collective public datasets from eight studies that are examining low‐grade gliomas and glioblastomas encompassing 4216 samples demonstrate the following distribution: somatic mutations were found in 8/4216 (0.19%) cases for DVL1, 12/4216 (0.28%) for DVL2 and 5/4216 (0.12%) for DVL3." (PMID 30468298, 2019).
major depressive disorder (3 papers, 2018 to 2024). An episode of depression lasting two or more weeks without an intervening episode of mania. "Moreover, DVL3 suppresses the expression of major proteins associated with AD and depression by inhibiting the activity of GSK3β." (PMID 37501340, 2024). "Moreover, we know that DVL3 is associated with two diseases: AD and depression." (PMID 37501340, 2024). "Using the CTD database, we found that DVL3 was closely related to both AD and depression." (PMID 37501340, 2024). "Therefore, our results indicate that a reduction in DVL3 expression downregulates GSK3β, which prevents AD and depression in PS2 MT mice." (PMID 37501340, 2024). "The results indicate that DVL3 could be a significant key regulator of both Alzheimer's disease and depression." (PMID 37501340, 2024). "Moreover, both depression and AD have connections with GSK3β and DVL3." (PMID 37501340, 2024). "Therefore, our results indicate that decreased levels of DVL3 could provide a link between AD and depression." (PMID 37501340, 2024). "As the expression of DVL3 was decreased in PS2 knock‐in mice, the expression of AD and depression‐related proteins were increased." (PMID 37501340, 2024).
melanoma (3 papers, 2017 to 2024). A malignant, usually aggressive tumor composed of atypical, neoplastic melanocytes. "In order to assess signal expression levels of DVL3 and sFRP3, the immunostains were compared to expression levels of normal frontal cortex and white matter, placenta, and human malignant melanoma tissue." (PMID 29200599, 2017). "Interestingly, the expression of two genes encoding direct targets ubiquitinated by RNF43, namely, DVL3 and VANGL1, increased during melanoma progression and high expression in both cases correlates with bad prognosis and shorter overall survival." (PMID 34702444, 2021).
anencephaly (2 papers, 2018 to 2021). A rare neural tube defect during pregnancy, resulting in the absence of a large portion of the brain and skull in the fetus. "Five anencephaly cases carried rare or novel CELSR1 missense variants, three of whom carried additional rare potentially damaging PCP variants: 01F377 (CELSR1 c.6362G>A and PRICKLE4 c.730C>G), 2F07 (CELSR1 c.8807C>T and DVL3 c.1622C>T), 618F05 (CELSR1 c.8282C>T and SCRIB c.3979G>A)." (PMID 29205322, 2018). "Discovery of heterozygous digenic deleterious variants in human NTD cases with spina bifida (i.e. PTK7/ SCRIB) and anencephaly (i.e. CELSR1/SCRIB; CELSR1/DVL3) strongly support the strategy of screening PCP genes to discover risk alleles contributing to human NTDs3,12." (PMID 33574475, 2021).
astrocytoma (2 papers, 2019 to 2021). "Statistical analysis revealed that LOH of DVL3 gene was significantly more frequent in glioblastomas as compared with astrocytomas of lower grades (P = 0.007)." (PMID 30468298, 2019). "Key regulators of the Wnt signalling, DVL1, DVL2 and DVL3, in astrocytomas of different malignancy grades were investigated." (PMID 30468298, 2019). "In all grade I and II astrocytomas samples, DVL3 expression was characterized as weak, while 82.4% of glioblastomas showed moderate and strong expression levels." (PMID 30468298, 2019). "Glioblastoma had highest proportion of cells with moderate and strong expression (82.4%), while astrocytomas grade I and II were characterized with weak DVL3 expression, as none of the analysed samples showed more than 50% of positive cells in the tumour hot spot area." (PMID 30468298, 2019).
cholangiocarcinoma (2 papers, 2018 to 2022). A carcinoma that arises from the intrahepatic biliary tree (intrahepatic cholangiocarcinoma) or from the junction, or adjacent to the junction, of the right and left hepatic ducts (hilar cholangiocarcinoma). "Taken together, the results demonstrate that EZH2 and DVL3/β-catenin are involved in the malignant behavior of cholangiocarcinoma, are associated with migration, invasion, distant metastasis, sphere formation, and tumor initiation and are regulated by let-7c." (PMID 29445149, 2018). "We next determined whether EZH2 and DVL3/β-catenin affect migration and invasion in cholangiocarcinoma." (PMID 29445149, 2018). "In addition, we reveal that let-7c enhances invasion and tumor growth of cholangiocarcinoma at distant sites in nude mice via the DVL3/β-catenin axis." (PMID 29445149, 2018). "This dual role in regulating cholangiocarcinoma can be imitated by regulating EZH2 and DVL3 expression." (PMID 29445149, 2018). "Taken together, our results reveal that the effect of let-7c on invasion and distant metastasis capacities of cholangiocarcinoma cells is, at least partially, mediated by EZH2 and the DVL3/β-catenin axis." (PMID 29445149, 2018). "The miRNA let-7c thus plays an important dual role in regulating tumorigenic and metastatic abilities of human cholangiocarcinoma through mechanisms involving EZH2 protein and the DVL3/β-catenin axis." (PMID 29445149, 2018). "This dual role in the regulation of cholangiocarcinoma could be mimicked by the regulation of EZH2 and DVL3 expression." (PMID 35943151, 2022). "To confirm whether EZH2 affects tumorigenesis capacity of cholangiocarcinoma, we transduced a lentivirus shRNA vector into TFK-1 cells in order to silence EZH2 and DVL3 genes and repeated the sphere formation and tumor-initiating assays." (PMID 29445149, 2018). "The result indicated that the mRNA expression of EZH2 and DVL3 was significantly increased in cholangiocarcinoma cells upon let-7c downregulation compared to the negative control group (P < 0.005 and 1.8125E−05, respectively)." (PMID 29445149, 2018).
colon cancer (2 papers, 2017 to 2019). "Gan et al57 found that DVL3 was accumulated in the nucleus in 36% of the analysed colon cancer samples." (PMID 30468298, 2019).
esophageal squamous cell carcinoma (2 papers, 2021 to 2022). Esophageal squamous cell carcinoma (ESCC) is a type of esophageal carcinoma (EC) that can affect any part of the esophagus, but is usually located in the upper or middle third. "In esophageal squamous cell carcinoma, the knockdown DVL3 accounts for the inhibition of the growth and promotion of apoptosis of tumor cells." (PMID 36614043, 2022).
glioblastoma (2 papers, 2017 to 2019). The most malignant astrocytic tumor (WHO grade IV). "It is also obvious that mutational burden is much more frequent in glioblastomas than low‐grade tumours and those amplifications are particularly associated to DVL3 gene and to glioblastomas." (PMID 30468298, 2019). "DVL3 was localized exclusively in the cytoplasm in 53% of glioblastomas, while 44% had the protein coexpressed in the cytoplasm and nucleus." (PMID 29200599, 2017). "Glioblastomas with strong expression of DVL3 will significantly more often have the protein in the nucleus." (PMID 29200599, 2017). "We analyzed expression levels of DVL3 and sFRP3 proteins in 34 glioblastomas with an emphasis on subcellular localizations." (PMID 29200599, 2017). "Our study aims to identify the status of Wnt signaling key proteins, DVL3 and sFRP3, in human glioblastoma, and search for their connection with clinicopathological data in order to offer potential diagnostic and prognostic biomarkers." (PMID 29200599, 2017). "The expression patterns of critical molecular components of Wnt signaling, sFRP3 and DVL3, were investigated in glioblastoma, the most aggressive form of primary brain tumors, with the aim to offer potential biomarkers." (PMID 29200599, 2017). "In our study, we demonstrated that glioblastomas had high content of moderate (52.4%) and strong (23.1%) expression levels of DVL3 protein." (PMID 29200599, 2017). "The present study investigated the involvement of two Wnt signaling pathway proteins, DVL3 and sFRP3, in glioblastoma and demonstrated for the first time their expression levels and relationships." (PMID 29200599, 2017). "Subcellular localization of the protein revealed that DVL3 was localized in cytoplasm in 53% of glioblastoma, while 44% of our total sample coexpressed the protein in the cytoplasm and nucleus." (PMID 29200599, 2017). "Glioblastomas with strong expression of DVL3 will significantly more often have the protein in the nucleus (P = 6.33 × 10−5)." (PMID 29200599, 2017). "We also tested tumors diagnosed as recurrent to the expression levels of both proteins and found that all recurrent cases showed moderate and strong sFRP3 expression, while DVL3 was moderately expressed in 78% of recurrent glioblastoma." (PMID 29200599, 2017). "DVL3 was localized in cytoplasm in 97% of glioblastomas, of which 44% coexpressed the protein in the nucleus." (PMID 29200599, 2017). "We also found the amplification of DVL3 gene in 8.6% of glioblastoma which could indicate different cellular roles for this gene." (PMID 30468298, 2019). "Majority of glioblastomas had moderate expression levels for both DVL3 (52.4%) and sFRP3 (52.3%)." (PMID 29200599, 2017). "Finally, we investigated the association of epidemiological characteristics and anatomical site of the glioblastoma patients to DVL3 and sFRP3 expression levels and localizations." (PMID 29200599, 2017). "We demonstrated that DVL3 and sFRP3 proteins were present in glioblastoma tissue samples." (PMID 29200599, 2017). "It opens doors for future mechanistic investigations on DVL3 and sFRP3 roles in glioblastoma." (PMID 29200599, 2017). "Besides gross deletions, DVL3 gene also showed amplifications in 8.6% of glioblastoma patients." (PMID 30468298, 2019). "Differences between age groups and levels or localizations of DVL3 and sFRP3 in glioblastoma were also not significant." (PMID 29200599, 2017). "As the correlation between the decreased protein expression of DVL3 and the presence of gross deletions has not been established, there is a possibility that the observed LOHs are the reflection of tumour heterogeneity occurring only in certain glioblastoma subtypes." (PMID 30468298, 2019). "Furthermore, deletions of DVL1 were found in seven glioblastomas and deletions of DVL2 in two glioblastomas, while deletions of DVL3 were not reported." (PMID 30468298, 2019).
Pleural effusion (2 papers, 2012 to 2014). The presence of an excessive amount of fluid in the pleural cavity. "The main purpose of this study was to determine the diagnostic capacity in pleural effusions of tumor markers DVL-3 mRNA and δ-catenin mRNA." (PMID 22461838, 2012). "Thus, detecting DVL-3 mRNA and δ-catenin mRNA in a pleural effusion can provide a supplement to TNM staging." (PMID 22461838, 2012).
squamous cell carcinoma (2 papers, 2014 to 2024). A carcinoma arising from squamous epithelial cells. "However, besides S100A16, miR-6884-5p was reported to regulate l lncRNA LINC01224 as competitive endogenous RNA (ceRNA), and miR-6884–5p/Dishevelled segment polarity protein 3 (DVL3) axis also activated Wnt/β-catenin signaling pathway in squamous cell carcinoma." (PMID 38271114, 2024).
alveolar rhabdomyosarcoma (1 paper, 2022). A rapidly growing malignant mesenchymal neoplasm. "Importantly, DVL1 and DVL3 also regulate proliferation in alveolar rhabdomyosarcoma (ARMS) cells." (PMID 35589804, 2022).
anaplastic large cell lymphoma (1 paper, 2016). Anaplastic large cell lymphoma (ALCL) is a rare and aggressive peripheral T-cell non-Hodgkin lymphoma, belonging to the group of CD30-positive lymphoproliferative disorders, which affects lymph nodes and extranodal sites. "LR DLBCLs were associated with duplications of DVL3, a member of the disheveled protein family which has been described to promote cell growth in ALK-positive anaplastic large cell lymphoma." (PMID 27276707, 2016).
aortic disorder (1 paper, 2024). Pathology involving the thoracic, thoracoabdominal, or abdominal aorta (including aneurysms). "We further identified two common variants (rs3812603 in NOTCH1 intron and—rs73185723 in DVL3) in association with CAVD, which further underlined the importance of this gene in relation to aortic disorders." (PMID 39057646, 2024).